PTBP1 (polypyrimidine tract binding protein 1)
Diseases named in the same sentence as PTBP1 in open-access papers (continued):
Sharing a sentence is not in itself a finding about the gene and the disease.
cancer (continued). "Altogether, our findings strongly suggested that c-Myc is essential for PTBP1 to sustain GC cancer stem-cell-like characteristics." (PMID 36635500, 2023). "In cancer cells, PTBP1 and PTBP2 promote the skipping of an exon of SRSF3, therefore impairing the autoregulation of SRSF3." (PMID 36833284, 2023). "Polypyrimidine tract binding protein (PTBP1) is an RNA-binding protein which plays important biological roles in diverse processes of cancer cells." (PMID 37724122, 2023). "In particular, PTBP1 regulates several pathways that play a key role in cancer growth and survival by modulating apoptosis and proliferation through alternative splicing of MCL1 and ADAR1." (PMID 36949664, 2023). "As expected, we showed that the depletion of PTBP1 impaired cancer stem-cell-like phenotypes, including spheroidization, clonogenicity, the expression of CSC markers." (PMID 36635500, 2023). "PTBP1 was known to act as a tumor-promotive regulator in various cancers, including gastric cancer, breast cancer, colon cancer, and lung cancer." (PMID 37724122, 2023). "As a ribosomal protein, PTBP1 promotes the development of various types of cancer by enhancing the stability of mRNA or the translation of oncogenic factors." (PMID 36635270, 2023). "Recent studies have shown that PTBP1 plays a vital role in the maintenance of cancer stem-cell phenotypes and alleviating chemotherapy resistance." (PMID 36635500, 2023). "PTBP1 is one of the most thoroughly investigated RBPs and plays a comprehensive role in cancer initiation, progression and cell apoptosis." (PMID 37633911, 2023). "Another RNA-binding protein, PTBP1, has been reported to regulate glycometabolism reprogramming in many sorts of cancers and specifically interact with sense probes." (PMID 36635270, 2023). "We observed that AGO1/2, EIF4A3, ELAVL1, and PTBP1 were the main RBPs acting in most of the cancer-related and gene regulation enriched pathways." (PMID 35805051, 2022). "We used The Cancer Genome Atlas, Gene Expression Omnibus, and Human Protein Atlas datasets, as well as several bioinformatics tools, to explore the role of PTBP1 in 33 tumor types." (PMID 36595978, 2022). "PTBP1 controls glycolysis, apoptosis, proliferation, tumorigenesis, invasion and migration in cancer." (PMID 35292107, 2022). "For the exploration of potential therapeutic targets, it is extremely important to examine the correlation between PTBP1 expression and various drugs in a pan-cancer analysis." (PMID 35600383, 2022). "As an important RNA-binding protein, PTBP1 plays a crucial role in RNA metabolism and the progression of numerous types of cancer." (PMID 35600383, 2022). "An increased ratio of PKM2/PKM1 mRNA in cancer cells is controlled by three heterogeneous nuclear ribonucleoproteins (hnRNPs) including PTBP1 (also known as hnRNPI), hnRNPA1 and hnRNPA2." (PMID 35292107, 2022). "Together, our results not only reinforce the notion of MALAT1 being functionally diverse in human cancers but also indicate that the functional module consisting of MALAT1, PTBP1, and PSF should be implicated in the pathogenesis of HCC." (PMID 36563164, 2022). "Spearman correlation analysis on the pan-cancer dataset from cBioPortal yielded 926 mRNAs co-expressed with PTBP1, 657 mRNAs co-expressed with PTBP2, and 874 mRNAs co-expressed with PTBP3 (|R| ≥ 0.4, p < 0.05)." (PMID 36203873, 2022). "Our data revealed that PTBP1 was significantly higher in LUAD cancer tissues compared with normal human lung tissue, consistent with previous studies." (PMID 35600383, 2022). "Oppositely, cancer-related tissues/cells manifest high Ptbp1 expression rates, as reported in studies." (PMID 35204777, 2022). "Downregulation of PTBP1 exerts anti-tubulin chemotherapeutics resistance in cancer cells by apoptotic evasion." (PMID 36293493, 2022). "We employed the public database and found that PTBP1 was significantly up-regulated in numerous human cancers, particularly LUAD." (PMID 35600383, 2022).
cancer (continued). "Knockdown of PTBP1 significantly induced upregulation of 175 and downregulation of 552 transcripts in cancer cells." (PMID 36357395, 2022). "It is well documented that abnormal PTBP1 expression leads to progression in various types of cancer." (PMID 35600383, 2022). "PTBP1 was originally identified as an SF and a promoter in multiple cancers by regulating oncogenes or tumor suppressors, including PKM2, MRP1, and FGFR1." (PMID 34290732, 2021). "While the oncogenic role of the PTBP1-mediated RNA splicing program has been demonstrated, the mechanism of PTBP1 regulation in cancer cells remains elusive." (PMID 34548489, 2021). "Function as an architectural scaffold sequestering PTBP1 in the perinucleolar compartment, thus modulating splicing of PTBP1 protein and promoting cancer cell survival (LLPS)." (PMID 33868368, 2021). "These TFs regulate critical genes (such as MAML2, CDK6, FAM84B and PTBP1) that play fundamental roles in cancer." (PMID 33537074, 2021). "For overall survival rate, in KIRC and LUAD, although high PTBP1 drives poorer outcome, the expression level of PTBP1 in normal tissues is very close to that in cancer tissues." (PMID 32207235, 2020). "We demonstrated the important roles of MTR4 in promoting HCC tumorigenesis and cancer metabolic reprogramming by regulating HCC relevant AS events through recruiting PTBP1 to its target pre-mRNAs." (PMID 32024842, 2020). "Cui et al30 confirmed that PTBP1 affects the apoptosis of cancer cells induced by chemotherapeutic drugs by regulating the expression of MCL." (PMID 32207235, 2020). "To explore the expression level of PTBP1 in several common cancers, we initially conducted bioinformatics analysis of the TCGA data set." (PMID 32207235, 2020). "Hypoxia also induces the expression of LUCAT1 lncRNA in cancer cells, which binds PTBP1 splicing factor resulting in alternative splicing inactivation of DNA damage-related tumour suppressors." (PMID 32536347, 2020). "To examine the possible therapeutic potential of decoy oligonucleotides against splicing factors, we designed a decoy oligonucleotide against another splicing factor, PTBP1, which is upregulated in several cancers and promotes pro-oncogenic splicing events." (PMID 30962446, 2019). "PTBP1 was more readily detected across lines and elevated levels of PTBP1 were observed in the vast majority of cancer lines compared to the normal HBECs." (PMID 30568224, 2019). "To explore the possible clinical associations between PTBP1 and AXL, we made use of the Oncomine cancer profiling database and conducting lung tissue microarray analysis." (PMID 31729427, 2019). "The splicing factor PTBP1 is positively correlated to the growth of various cancers and poor prognosis." (PMID 31065692, 2019). "Relevant to this, we demonstrate that inhibition of the oncogenic splicing factors SRSF1 and PTBP1 inhibits the oncogenic properties of cancer cells." (PMID 30962446, 2019). "The RRM1 of PTBP1 is therefore crucial for this interaction in mediating biological functions and cancer progression." (PMID 31729427, 2019). "Knockdown experiments of PTBP1 in cancer cells indicate that PTBP1 reduces hTERT FL splicing and telomerase activity." (PMID 30568224, 2019). "By employing hTERT as a model gene, we show the coordination of the splicing factors NOVA1 and PTBP1 in cancer by regulating telomerase that is expressed in the vast majority of cancer cell types." (PMID 30568224, 2019). "Since MCL1, PTBP1, and miR-101 are central regulators of various cellular processes, all have valuable therapeutic potentials in anti-cancer treatment." (PMID 29748555, 2018). "One of the identified candidates is PTBP1, a regulator of alternative splicing previously shown to promote cancer proliferation and metastasis." (PMID 29990503, 2018). "Our recent study indicated that PTBP1 functions as a novel oncogene and that PTBP1 promotes the Warburg effect in various types of cancer." (PMID 29695138, 2018).
cancer (continued). "The STR-enriched RNA PNCTR sequesters multiple copies of PTBP1 in the perinucleolar compartment, thus modulating splicing regulation function of this RNA-binding protein and promoting cancer cell survival." (PMID 30318443, 2018). "Expectedly, we also found the overexpression of PTBP1 in most cancers, including colon, gastric, and bladder." (PMID 28106737, 2017). "Based on such findings, we examined the relationship between miR-145 and c-Myc/PTBP1 in the cancer specific energy metabolism." (PMID 28106737, 2017). "We found that not only the miR-145/c-Myc/PTBP1/PKMs axis, but also the novel miR-145/KLF4/PTBP1/PKMs cascade operated in the regulation of cancer energy metabolism." (PMID 28380435, 2017). "To explore this possibility, we examined the effect of combination RNAi treatment by using miR-145, which can silence c-Myc expression and siR-PTBP1 to negate the action of the driver gene PTBP1 in cancer pathogenesis." (PMID 28106737, 2017). "Biochemically, the ectopic expression of miR-145 resulted in the appearance of the cleaved form of PARP and knockdown of PTBP1 induced the transition of the LC3BI to LC3BII in both types of cancer cells." (PMID 28106737, 2017). "PTBP1 promotes expression levels of cancer-dominant PKM2 by including exon 10 of the PKM gene to produce this isoform." (PMID 28380435, 2017). "Next, we examined the effect on cell growth by the combination treatment at the half maximal inhibitory concentration (IC50) of miR-145 as a replacement treatment and knockdown of PTBP1 by siR-PTBP1 in both cancer cells." (PMID 28106737, 2017). "Primary OSCC cells and CAL 27 cancer cell line had higher level of PTBP1 and PTBP2 than normal cells." (PMID 26416554, 2015). "Cancer cells take advantage of high levels of PTBP1 and PTBP2 to impair the inclusion of exon 4, thereby allowing the overexpression of full length SRSF3 and promoting cell proliferation and transformation." (PMID 26416554, 2015). "The regulatory regions of Polypyrimidine Tract Binding protein 1 (PTB), another cancer-associated splicing factor, bind to ERα in tamoxifen but not E2 treated cells and E2 induces its expression only after 24 hours." (PMID 23758675, 2013). "Previously, PTBP1 expression has been correlated with increases in proliferation and metastatic potential of cancer cells; however, this effect varies in different cell lines." (PMID 22911749, 2012). "Additionally, we identified that the mRNA expression of splicing factors RBM47 and PTBP1 positively correlates with KRAS E4 inclusion rates in cancer tissues and confirmed their roles in enhancing E4 inclusion in KRAS mRNA." (PMID 41368203, 2026). "Overall, our findings indicate that RBM47 and PTBP1 regulate the alternative splicing of KRAS E4 in human cancers, and that the resulting KRAS4A splicing isoforms may promote cancer cell proliferation and metastasis." (PMID 41368203, 2026). "The RNA-binding protein polypyrimidine tract-binding protein 1 (PTBP1) facilitates tumor progression in various cancers by interacting with mRNAs of key oncogenes and tumor suppressors, thereby regulating their mRNA stability, alternative splicing, and protein translation." (PMID 41313521, 2025). "We summarise the clinical translational potential of PTBP1 research as follows: potential therapeutic targets due to the critical role of PTBP1 in the progression of various cancers; factors and non‐coding RNAs related to its regulatory process have become new potential therapeutic targets." (PMID 40579921, 2025). "Therefore, by revealing the expression mechanism of PTBP1 and the interaction between PTBP1 and its target RNAs, new ideas or methods can be provided to find new targets for cancer therapy." (PMID 40579921, 2025). "However, the precise mechanisms of PTBP1’s role in additional cancer types remain inadequately understood, necessitating further comprehensive investigations." (PMID 40296916, 2025).
cancer (continued). "Potential as a biomarker, the status of PTBP1 may serve as a biomarker of prognosis and response to treatment in cancer patients, helping to assess patient response to treatment and guiding clinical decision‐making." (PMID 40579921, 2025). "An in‐depth investigation of the function of PTBP1 will not only help to reveal the basic mechanism of RNA cellular localization, but also has the potential to provide new ideas and strategies for the treatment of related cancers." (PMID 40579921, 2025). "miR‐145 hinders tumorigenesis by interfering with the Warburg effect (inhibiting glycolytic dependence), suggesting that PTBP1 may antagonise its function to maintain the metabolic dominance of cancer cells." (PMID 40579921, 2025). "PTBP1 is reportedly to be participated in metabolic reprogramming in cancer progression due to controlling biogenesis of Pyruvate kinase M2 subtype (PKM2), a crucial member of pyruvate kinase which is required for the lactate production during metabolic reprogramming in cancer." (PMID 38341427, 2024). "Overall, the combined analysis of PTBP1 expression and methylation patterns suggests that PTBP1 may have a significant role in the regulation of gene expression and the development of various cancer types." (PMID 38918441, 2024). "Amazingly, CD276 expression was positively correlated with PTBP1 expression in most cancers." (PMID 38918441, 2024). "As PTBP1 has been reported to have pro-apoptotic activities, such sequestration mechanism may also help cancer cells to avoid programed cell death." (PMID 38281066, 2024). "Furthermore, we utilized a uni-Cox regression model to examine the correlation between PTBP1 expression in various cancer types and disease-specific survival (DSS) prognosis." (PMID 38918441, 2024). "In cancer cells, PTBP1 is mainly involved in the process of glycolysis." (PMID 38918441, 2024). "However, the involvement of PTBP1 in cellular senescence, a key biological process in aging and cancer suppression, remains to be clarified." (PMID 39057099, 2024). "This revealed an important function of PTBP1 in GC, for cancer-specific metabolism." (PMID 38247832, 2024). "Finally, the correlation of these genes with PTBP1 in different cancers was compared using the Pearson coefficient." (PMID 38918441, 2024). "In summary, PTBP1 emerges as a promising prognostic marker across diverse cancer types." (PMID 38918441, 2024). "PTBP1 expression and methylation play an important role in a variety of cancers." (PMID 38918441, 2024). "Treatment with miR‐124 activated neuronal differentiation of a mouse cancer cell line by targeting polypyrimidine tract binding protein 1 (PTB1), which in turn increased the expression of a splice variant of PTB2, important for correct splicing of several neuronal genes." (PMID 37702572, 2024). "In order to determine the difference in PTBP1 expression between tumors and normal tissues, the TCGA database combined with the GTEx database was used to analyze PTBP1 mRNA levels in tumors and normal tissues of various cancer types." (PMID 38918441, 2024). "The result suggests that PTBP1 expression at the pan-cancer level may inhibit drug resistance in tumour cells." (PMID 38918441, 2024). "Furthermore, we constructed a survival model and plotted ROC curves to assess the predictive performance of PTBP1 expression for 1-year, 3-year, and 5-year survival in the three cancer types (ACC, LGG, MESO)." (PMID 38918441, 2024). "Well, with the comprehensive analysis of PTBP1‐related studies, we found that different functions and clinical relevance that PTBP1 may display among different cancers." (PMID 39287090, 2024). "However, little is known about the function of PTBP1 in the regulation of cytoplasmic export of RNA in cancer cells." (PMID 36635270, 2023).
cancer (continued). "Furthermore, overexpression of miR-1 and miR-133b also resulted in autophagic cell death through the silencing of polypyrimidine tract-binding protein 1 (PTBP1), a positive regulator of cancer-specific energy metabolism." (PMID 36765536, 2023). "Given the possible relationship between PTBP1 and GCSCs, we analysed whether PTBP1 affects cancer stem-cell-like phenotypes." (PMID 36635500, 2023). "In contrast, PTBP1 overexpression preserved cancer stem-cell-like characteristics." (PMID 36635500, 2023). "In cancer cells, the most important process involving PTBP1 is glycolysis." (PMID 36508323, 2023). "The role of PTBP1 in PKM splicing is already known in several cancer types." (PMID 36508323, 2023). "PTBP1 expression was significantly positively corelated with IQGAP3 expression in human cancer." (PMID 35274003, 2022). "Furthermore, cancer cells died much more quickly with the knockdown of PTBP1 and combinational treatments of decitabine and carboplatin or navitoclax." (PMID 36357395, 2022). "Interestingly, when we analyzed the expression correlation of PTBPs, we found that PTBP1/3 appeared to have opposite expression trends to PTBP2 in pan-cancer." (PMID 36203873, 2022). "Overall, these results demonstrated that PTBP1 may be a transcription factor for IQGAP3 in different cancer types." (PMID 35274003, 2022). "The cancer cases were divided into 2 groups based on the expression levels of PTBP1." (PMID 36595978, 2022). "PTBP1 was positively correlated with IQGAP3 expression in diverse cancer types." (PMID 35274003, 2022). "Thus, we carried out a systematic pan-cancer analysis to explore the relationship between PTBP1 and cancer." (PMID 36595978, 2022). "Studies focusing on the function of PTBP1 in the modulation of RNA splicing in the nucleus was also found that it may play crucial oncogenic roles in the progression of various cancers." (PMID 35600383, 2022). "Therefore, we aimed to conduct a pan-cancer analysis of PTBP1 using the cancer genome atlas (TCGA) and Gene Expression Omnibus (GEO) databases." (PMID 36595978, 2022). "Polypyrimidine tract-binding protein 1 (PTBP1) is reported as a tumor promoter in some cancers." (PMID 34716285, 2021). "In contrast, PTBP1 was significantly higher in the FL-TERT-expressing group for 10/33 cancer types." (PMID 33924498, 2021). "In addition, polypyrimidine tract binding protein 1 (PTB1) is a positive regulator of the Warburg effect in cancer cells by regulating the PKM2 expression." (PMID 34887764, 2021). "RNA‐binding protein PTBP1 has been identified as an oncogene in various cancers." (PMID 32207235, 2020). "According to previous studies on PTBP1 in cancer, we found that PTBP1 could reduce the stability of mRNA by binding to it in a variety of cancer cells, which further negatively regulates the expression of the target gene." (PMID 32207235, 2020). "PTBP1 acts as an oncogene in many cancers through regulating alternative splicing." (PMID 31964396, 2020). "However, the sequence of the binding sites of PTBP1 to pre-mRNA is conserved and cannot explain the aberrant splicing events in cancer cells." (PMID 32024842, 2020). "Besides, former studies have uncovered that PTBP1 undergo regulation of non‐coding RNAs in the progression of various cancers." (PMID 32207235, 2020). "Previous reports have shown that PTBP1 acts as a tumor promoter in several cancers." (PMID 31964396, 2020). "In addition, lncRNA PNCTR can bind to PTBP1 and modulate its regulation of splicing of mRNAs related to cancer cell survival." (PMID 31964396, 2020). "Increasing evidence has demonstrated that PTBP1 plays a critical role in the malignant characteristics of tumours and may be a target for cancer treatment." (PMID 32207235, 2020). "However, only BLCA and LIHC cohorts showed a separation between the normal and cancer samples, and the expression of PTBP1 in the normal samples falls within the 10%‐90% range of the cancer cohort in other cancer types (H‐I)." (PMID 32207235, 2020).